IL6 (interleukin 6)
Diseases named in the same sentence as IL6 in open-access papers (continued):
Sharing a sentence is not in itself a finding about the gene and the disease.
tumor (continued). "Tumor cells express many factors including CCL2 (under hypoxic conditions), M-CSF or GM-CSF, IL-10, TGF-β, and IL-6, all of which favor the recruitment and generation of TAMs." (PMID 29868007, 2018). "In many cases, TAM-derived IL-6 and other cytokines activate STAT3 to promote tumor development by inducing proliferation and inhibiting apoptosis." (PMID 30271456, 2018). "qRT–PCR demonstrated that the tumour tissue in the CDDP group showed an increased expression of P21 and SASP genes, such as IL-1β, IL-6 and IL-8." (PMID 29449532, 2018). "Tumor cells are able to secret copious cytokines, like SDF-1, IL-6, and platelet-derived growth factor (PDGF), that can induce MSCs to migrate to tumor tissue." (PMID 29386041, 2018). "The tumor promoting functions of TIMs are typically activated by TLR triggering and binding of cytokines and growth factors such as IFN-γ, IL-4, IL-6, IL-10, IL-13, and TGF-β to their responding receptor." (PMID 30233579, 2018). "Collectively, oncogenic G3BP1 serves as a signaling linkage molecule from upstream IL-6/EGF elicited stimulations to downstream STAT3 signaling, eventually contributing to promote tumor cell growth and metastasis in RCC." (PMID 29717134, 2018). "As FAP expression was associated with EGR1 upregulation, we assessed the presence of nuclear EGR1 in TAMs in 4T1 tumours grown in WT and Il6−/− mice and found a significant reduction of nuclear EGR1 in the TAMs of Il6−/− mice." (PMID 30054470, 2018). "AIRE by inducing malignancy factor IL-6 leads to more of inflammation and lymphadenopathy in AIRE+/+ mice; however, a small benign tumor is observed in AIRE−/− mice." (PMID 29795364, 2018). "By releasing IL-6, MDSCs elicit STAT3 activation and invasive capabilities of BC cells, with subsequent increase in tumor and metastasis burden." (PMID 30200242, 2018). "Plasma levels of haptoglobin, IL-6 and SAA correlated with the number of lung metastases in tumour-bearing mice." (PMID 29788918, 2018). "Cytokine levels relative to tumor characteristics were assessed for VEGF, MCP-1, PAI-1, TNF-α, IL-6, transforming growth factor- (TGF-) β, and IL-10 by ELISA at the end of 72 h of coculture." (PMID 30034291, 2018). "Among a group of genes responsible for cell contact independent mechanism of tumor promotion and reportedly impacting on cancer progression, IDO and IL-6 genes were the only ones consistently overexpressed in PCa cells upon stimulation with IFN-γ or TNF-α." (PMID 29896191, 2018). "We have demonstrated IL-6 to be a key regulator of the FAP+ HO-1+ macrophage phenotype, and this cytokine is also expressed directly by the macrophages in 4T1 tumours." (PMID 30054470, 2018). "Among these mediators are pro-inflammatory cytokines such as prostaglandin E2, IL-6, TNF, IFNγ, TRAF6, IL-1α, IL-1β and other tumour-derived catabolic factors such as activin and myostatin." (PMID 30061533, 2018). "Numerous cytokines, such as CXCL8, IL-6, and CXCL5, trigger inflammatory responses by recruiting and activating relevant inflammation cells in the tumor foci resulting in tumor growth, progression, and immunosuppression." (PMID 29636079, 2018). "After CM stimulation, the tumor educated macrophages (TEM) decreased the expression of M1 macrophage markers, such as IL-1b, IL-6 and increased the expression of M2 macrophage markers including Arg1 and CD163 compared with M0 macrophage." (PMID 30180849, 2018). "It is reported that the GBM-secreted inflammatory cytokine interleukin (IL)-6 acts on liver cells, inducing them to secrete high levels of CRP, which reaches the GBM tumor through the blood circulation and is accumulated in tumor tissues." (PMID 29513714, 2018). "The interaction between BM‐MSCs and OS cells is bidirectional: the mesenchymal stroma activated by tumour cells secrete higher levels of IL‐6, IL‐8, GRO‐α and MCP‐1 in the tumour microenvironment." (PMID 29517849, 2018).
tumor (continued). "Tumor cell-derived EVs are potent stimulators of MMP-9, IL-6, and TGF-β1 and induce the secretion of extracellular EMMPRIN, which play active roles in driving immune evasion, invasion and inflammation in the tumor microenvironment." (PMID 30322133, 2018). "Decreased levels of TG have been connected with increased circulating levels of IL-6, TNF-α which are thought to induced the tumor cell proliferation and inhibit apoptosis." (PMID 30400953, 2018). "The activation of NF-κB has been observed in most human cancers, such as OSCC, and can stimulate IL-6 expression, thus activating STAT3 and subsequent tumour growth and metastasis." (PMID 30248985, 2018). "Although the most commonly studied cytokines regulated by MK2 are IL-1β, IL-6, and TNF-α, here we showed that MMM are also substantially decreased in tumor cells and in tumors with mixed cell populations upon MK2 inhibition." (PMID 30298062, 2018). "This recruitment is increased by various secreted factors such as CCL21, CXCL12, CCL27, IL6 and KAI1, which also induce lymphangiogenesis in tumor-draining lymph nodes (LNs)." (PMID 29898755, 2018). "Inhibition of IL-6 attenuated MDSC recruitment in the tumors and spleens of tumor-bearing mice, increased CD3+ TILs, and increased CD8+ cytotoxic cells in non-irradiated tumors of mice that underwent ADT or local RT." (PMID 30587810, 2018). "The observed consequences of reduced GM-CSF and IL-6 expression were impaired MDSC accumulation, reestablishment of anti-tumor IFN-γ+ T-cell activity, and hampered tumor angiogenesis." (PMID 30555465, 2018). "TAMs secrete cytokines, including interleukin-6 (IL-6), interleukin-10 (IL-10), tumor necrosis factor-α (TNF-α), and interferon-γ, which have been shown to promote tumor cell growth." (PMID 30034397, 2018). "The hepatocyte-Tim-3 receptor activates NF-kappa B phosphorylation, which in turn stimulates IL-6 secretion and STAT3 phosphorylation, resulting in tumor growth both in vitro and in vivo." (PMID 30175384, 2018). "We addressed the role of inflammatory stimuli in the release of PCa-specific, tumor-derived soluble factors (PCa-TDSFs) already reported to be mediators of PCa morbidity, such as indoleamine 2,3-dioxygenase (IDO) and interleukin (IL)-6." (PMID 29896191, 2018). "The immunohistochemical staining results of IL-6, p-STAT3 and NF-κB showed that the expression of these three proteins were significantly reduced in mouse tumor tissue sections of the Res group." (PMID 29390972, 2018). "Tumor inoculation slightly upregulated serum IFN-α and IL-6 production, but these diminished quickly." (PMID 29568358, 2018). "Interleukin-6 is also responsible for inducing VEGF synthesis, and both cytokines are able to induce tumor angiogenesis." (PMID 30123112, 2018). "M2 TAMs support tumor progression by directly stimulating the growth of cancer cells through the production of growth factors, including EGF, TNFα, IL-6." (PMID 30356656, 2018). "We have previously presented evidence of the important roles of interleukin-6 (IL-6) and chemokine (C-C motif) ligand 5 (CCL5) in TNBC tumor growth and metastasis." (PMID 29898755, 2018). "Pro-inflammatory (such as IL-6 and TNF-α) and proliferative (like leptin and insulin) factors are considered as tumor growth favoring molecules." (PMID 29568521, 2018). "We previously observed that CD200 overexpression by CD200tg hosts resulted in increased tumor-induced IFN-γ and decreased IL-6 responses further documenting efficiency of CD200fc as CD200 mimetic." (PMID 29721190, 2018). "TNF, IL6 and ANGPT2 were expressed equally by both DLD1 and SKBR7 xenografts, whereas higher levels of IL1B, IL4, IL13 and VEGFA were found in DLD1 tumours." (PMID 29367702, 2018).
tumor (continued). "IL6 is a critical cytokine exerting multiple physiological effects in inflammation and immune regulation, which could be secreted by a range of cell types including monocytes, mast cells, lymphocytes, macrophages, endothelial cells, keratinocytes, tumor cell lines, and fibroblasts." (PMID 30662576, 2018). "TLR9/NF-κB signaling stimulated macrophages to release IL-6, which in turn jump-started proangiogenic and tolerogenic STAT3 signaling leading to tumor recurrence." (PMID 29541413, 2018). "Src can increase pro-inflammatory cytokines production for tumor development and activate survival effectors for chemoresistance, including TNF-α, IL-1β, IL6, phosphoinositide 3-kinases (PI3Ks), AKT and STAT3." (PMID 30473665, 2018). "ROS activate NF-κB, TNF-α, and STAT3 signaling pathways in inflammatory cells and tumor cells to release TNF, NOX2, IL-6, IL-2, IL-8, and CXCL12 involved in the change of TME." (PMID 29770167, 2018). "Particularly notable in that study was the enhanced production of IL-6, IL-8 and CXCL1 in the tumor lines resistant to anti-VEGF treatment, the same cytokines that were upregulated in stromal cells upon LTβR stimulation in our study." (PMID 29983872, 2018). "NexturastatA was able to reduce primary tumor growth, as well as inhibit tumor invasion and modify the expression of EMT-specific gene signature, even in presence of metastasis-promoting cytokine IL6." (PMID 30400822, 2018). "Immunohistochemistry (IHC) study was performed on type I EC tumor samples using five adipokines (SPARC, RBP4 (Retinol Binding Protein 4), adiponectin, TNF α, IL-6) and hormonal receptors (estrogen receptor and progesterone receptor)." (PMID 28505082, 2017). "In addition, mast cells may promote inflammation, inhibition of tumor cell growth, and tumor cell apoptosis by releasing interleukin (IL)-1, IL-4, IL-6, IL-8, monocyte chemotactic protein-3 and-4 (MCP-3 and MCP-4), transforming growth factor beta (TGF-β), and chymase." (PMID 29137286, 2017). "Through binding with IL-6R, IL-6 activates JAK-STAT3 signaling pathway and in turn confers tumor cells proliferation advantages." (PMID 28036277, 2017). "Significant differences of IL-1β, IL-6, TNF-α and HGF were also detected in the comparison between tumor and non tumor HF and LF-HC bearing mice." (PMID 28881825, 2017). "Tumor epithelium may also promote the downregulation of the tumor-suppressor p62 in stromal fibroblasts, leading to a decrease in mTORC1 activity and c-Myc expression, in turn producing impairment in the mechanism of metabolic detoxification and the subsequent release of ROS and IL-6." (PMID 28270771, 2017). "Tumor irradiation also induces TGF-β and IL-6 expression, thereby triggering the ATM-dependent DNA damage response and repair pathway in cancer cells." (PMID 28928376, 2017). "Instead, emerging evidence strongly suggests that activated immune cells within the tumor microenvironment promote EMT in IBC cells by secreting proinflammatory cytokines including TNF, IL6, and TGF-β." (PMID 28607534, 2017). "The increase in IL-6, IL-12, CCL2, CCL3, CCL5, CXCL9 levels would a priori predict for elevated levels of M1 type macrophages in the tumor, which independently validates our prior IHC staining findings." (PMID 29137331, 2017). "This study further demonstrated that serum Shh and IL-6 levels (both levels are higher than baseline levels) remained a significant predictor of EFS and OS when adjusted for other known factors i.e. tumor grade, lymph node status and progression." (PMID 28496132, 2017). "For example, IL-6 and TGF-β are produced and secreted by stromal cells of the tumor microenvironment." (PMID 28680090, 2017). "Secreting cytokines, IL-6 and CXCL7 by MSCs can enhance CSCs proliferation to facilitate the tumor growth." (PMID 28145881, 2017). "After tumor inoculation, MIC-1 levels increased earlier than IL-6 and both cytokines were elevated before MuRF-1/MAFbx expression increased." (PMID 28475119, 2017).
tumor (continued). "Numerous studies have indicated that tumor cells exhibit constitutive production of TNF-α proinflammatory cytokines, IL-1α, IL-6, and GM-CSF (macrophage-granulocyte colony-stimulating factor)." (PMID 28785138, 2017). "We have recently shown that paracrine IL-6 signaling between DCIS cells and CAFs facilitates tumor cell growth and migration in part through cathepsin B-mediated ECM degradation." (PMID 28506312, 2017). "Inflammatory cells in the tumor stroma interact with tumor cells in a bi-directional way via cytokines, such as IL6, IL8 and many others, which can promote tumor progression or mediate an immune response to the neoplastic cells." (PMID 28821810, 2017). "Tumor associated macrophages produce high amounts of cytokines such as interleukin-6 (IL-6), interleukin-8 (IL-8), monocyte chemotactic protein 1 (MCP-1) and tumor necrosis factor alpha (TNFα) to alter the tumor progression in different ways." (PMID 28832545, 2017). "In response to different stimuli including IL-6, TGFβ, CCL20, IL-23, IL-1β, and so on, especially under cancer microenvironments, Th17 cells can mediate tumor regression or tumor promotion." (PMID 29379802, 2017). "The tumor stromal cells expressing α-SMA, CD68, CD163, and IL-6 were evaluated in B viral multistep hepatocarcinogenesis." (PMID 28114366, 2017). "The in vivo relevance of these findings also demonstrated that deficiency in EP2 suppresses expressions of pro-inflammatory molecules, such as IL-6 and TNF-α, and factors supporting tumor cell growth, such as osteopontin, in lesions." (PMID 29259703, 2017). "In the present study, we found that IL-6 neutralizating antibody partly suppressed the STAT3 or JAK2 phosphorylation, which suggested that IL-6 contributed partially to the tumor-promoting effect of CAFs on GC cells." (PMID 28186964, 2017). "Many genes account for several aspects of the endothelial response, such as VEGFA, IL6 and TYMP for tumor angiogenesis, and S1PR1 for development and cell differentiation." (PMID 29088816, 2017). "MDSCs are recruited and regulated by multiple inflammatory mediators such as IL-1β, IL-6, and PGE2, which are released by tumor cells and stromal cells in an autocrine or paracrine fashion." (PMID 28360909, 2017). "Increasing evidence from functional studies indicates that GP130-mediated IL-6/STAT3 signaling activation contributes to tumor invasion and angiogenesis which are essential for tumor metastasis." (PMID 28672024, 2017). "The inflammatory cytokines such as G-CSF, IL-6 and TGF-β1 can induce N2 phenotype of neutrophils in bone marrow and tumor microenvironment." (PMID 28432279, 2017). "Excess adipose tissue leads to increased secretion of IGF-1, IL6, leptin and TGF-α which can promote tumor growth." (PMID 28768896, 2017). "IL-6, one of SASP factors, is a pro-inflammatory signaling protein that encourages tumor growth, and exerts its oncogenic activity by triggering downstream STAT-3 and ERK pathways." (PMID 28273155, 2017). "Immunoreactive IL-6, STAT3 and HIF1 cell numbers were markedly reduced in IL-6 knockdown tumor tissues." (PMID 28878571, 2017). "Most of the tumor-infiltrating hematopoietic/immune cells stimulate a persistent cycle of damage and repair in tumor tissue to generate a tumor-promoting inflammation by producing tumor-supporting cytokines including TNF, IL1, and IL6." (PMID 28039479, 2017). "The results showed that survivin helps the tumor-like proliferation of RA-FLS and is involved in the secretion of the proinflammatory cytokine IL-6 and MMPs." (PMID 28337018, 2017). "The protein expression of IL-6, TGF-β and α-SMA in tumor tissues from BALB/c athymic nude mouse was determined by Western Blots." (PMID 28819126, 2017). "Chemokines and cytokines including CCL2, CXCL12, CSF1, CCL5, CCL22, IL6 and TGFB3 are secreted by primary tumor cells to recruit immune cells to escape from anti-tumor immune responses." (PMID 28591712, 2017).
tumor (continued). "The cytokines in the tumor microenvironment can either promote antitumor immunity (IL-12, IFN-γ), enhance tumor development and progression (IL-6, IL-17, IL-23), or influence the cancer cell growth and survival (TRAIL, FasL, TNF-α, TGF-β, IL-6)." (PMID 28101811, 2017). "A number of cytokines, in particular IL-6, IL-8 and MCP-1, were elevated in patient plasma, tumor tissue and cultured tumor cells." (PMID 28389503, 2017). "EpCAM, K19 or CD133 expression also showed a significant correlation with those of tumor stromal CD68 (+)/CD163 (+) TAMs and IL-6 (+) stromal cells." (PMID 28114366, 2017). "A crucial role of IL-6 in the pathogenesis of CRC has been suggested as serum IL-6 levels were significantly increased in patients with CRC and correlated with tumor size and disease status." (PMID 28852270, 2017). "Employing this approach, they recognized a core of nine cytokines that consistently correlated with efficacious tumour suppression: IL-12p70, IFN-γ, IL-1α, IL-1β, IL-2, IL-3, IL-6, CXCL10, and CXCL9." (PMID 29089667, 2017). "On the one hand, Th17 cells can induce the production of IL-6; this activates the oncogene signal transducer and activator of transcription (STAT) 3, which then upregulates genes that induce tumor angiogenesis." (PMID 28796055, 2017). "In TLR4+/+ tumor-bearing mice, the levels of TNF-α and IL-6 in APS and LPS groups were significantly higher than those in NS and ADM TLR4+/+ groups (P < 0.05)." (PMID 28303957, 2017). "Classically, Th1 cytokines, such as interleukin-6 (IL-6), IL-12, tumor necrosis factor-α (TNF-α), and interferon-γ (IFN-γ), promote immune responses to intracellular pathogens and tumor cells." (PMID 28858203, 2017). "Among these differentially expressed genes, pro-inflammatory cytokines, such as IL6, CXCL1, CXCL5, CXCL8, and CSF2 were further validated as significantly downregulated in WCE-treated PC-3 and DU145 tumor tissues." (PMID 29142311, 2017). "Western blots confirmed significant increases in IL6 and IL8 protein levels in these “recurrent” tumor xenografts for the experimental points." (PMID 28542439, 2017). "IL-6 from infiltrating macrophages in the pancreata of PDAC transgenic mice activated transcription factor STAT3 in pancreatic tumor cells, promoting tumor development." (PMID 29379802, 2017). "In all the tumor tissues overexpressing PIM1/2, we detected a clear increment in the expression of IL-6, while NFAT2 was clearly increased and we observed an increase in two NFAT2 targets, cMYC and OSM." (PMID 28938604, 2017). "Using our 3D pathomimetic MAME cultures, we identified a divergent interplay between tumor-suppressive MEPs and tumor-promoting CAFs that involves PAI-1, uPA/uPAR, and IL-6 and that alters the cellular and molecular phenotype of DCIS." (PMID 28506312, 2017). "In the subcutaneous tumor model, tumor-bearing mice show elevated TNF-α, IL-6 and activin A levels that up regulate ubiquitin ligases such as muscle ring finger-1 (MuRF1) and Atrogin-1 mRNA expression in gastrocnemius muscles." (PMID 29033844, 2017). "We did, however, observe significant changes based on tumor status in inflammatory cytokines (IFN-γ, IL-6, IL-5, IL-2, IL-10) and a growth factor (FGF-basic)." (PMID 27893434, 2017). "IL-6 expression in OSCC has been related to high lymph node metastatic rates and poor tumour differentiation, especially in male patients." (PMID 28381274, 2017). "Previous studies have shown that in tumor-bearing mice, multiple inflammatory mediators, including interleukin-1β (IL-1β), IL-6, and prostaglandin E2 (PEG2), produced by tumor cells induce the accumulation of MDSCs in the tumor microenvironment of bone marrow." (PMID 29234328, 2017). "Based on the blots, it appeared that each inhibitor and the combination of inhibitors reduced expression of IL-6, TGF-β and α-SMA protein in tumor tissues isolated from the mice injected with CMT-167, MF and CMT + MF." (PMID 28819126, 2017).